GJB1 (gap junction protein beta 1)
Diseases named in the same sentence as GJB1 in open-access papers (continued):
Sharing a sentence is not in itself a finding about the gene and the disease.
liver fibrosis (2 papers, 2011 to 2023). "Cxcl12 is a gene encoding a chemokine modulating the progression of liver fibrosis through its action on hepatic stellate cells, while Gjb1 encodes a gap junction membrane channel protein which plays an important role in the regulation of signal transfer and growth control in the liver." (PMID 21864415, 2011).
Parkinson disease (2 papers, 2024 to 2026). A progressive degenerative disorder of the central nervous system characterized by loss of dopamine producing neurons in the substantia nigra and the presence of Lewy bodies in the substantia nigra and locus coeruleus. "Knockdown of lncRNA NEAT1 downregulated Cx32 expression via the promotion of miR-1301-3p, a suppressor of Gjb1 (Cx32); suppressed the α-synuclein-induced inflammatory response; and reduced apoptosis in a cellular Parkinson’s disease (PD) model." (PMID 38892334, 2024).
renal carcinoma (2 papers, 2019 to 2023). A carcinoma arising from the epithelium of the renal parenchyma or the renal pelvis. "GJB1 has been associated with PCa and has been identified as a prognostic marker for renal cancer." (PMID 36765747, 2023).
Seizure (2 papers, 2022 to 2025). A seizure is an intermittent abnormality of nervous system physiology characterized by a transient occurrence of signs and/or symptoms due to abnormal excessive or synchronous neuronal activity in the brain. "The role of GJB1 mRNA during epileptic seizures and the involvement of Cx32 in epileptic processes have yet to be confirmed." (PMID 40217413, 2025). "No increase in GJB1 mRNA transcription was observed in the hippocampus during the initial and mid-term stages of focal seizures in the kindling model." (PMID 40217413, 2025).
benign prostatic hyperplasia (1 paper, 2023). A non-cancerous nodular enlargement of the prostate gland. "Expression levels of GJB1 protein (aka Connexin 32, CX32) were found to be the same in PCa and benign prostatic hyperplasia samples." (PMID 36765747, 2023).
Charcot-Marie-Tooth neuropathy (1 paper, 2021). "The second most common form of Charcot-Marie-Tooth neuropathy (CMT), X-linked CMT type X1 (CMTX1), is caused by coding and non-coding mutations in the gap junction beta 1 (GJB1) gene." (PMID 34089394, 2021).
endometriosis (1 paper, 2023). The growth of functional endometrial tissue in anatomic sites outside the uterine body. "The difference in the results of dataset GSE7305 demonstrated that all NRDEGs were statistically significant, and the expression levels of C7, HOOK1, PKP3, AHR, GJB1, and MYO6 in different groups of endometriosis dataset GSE7305 were statistically significant (P < 0.001)." (PMID 37817158, 2023).
lung tumours (1 paper, 2019). "However, for GJB1 encoding Cx32, whose knockout mice are more susceptible to lung tumour formation, only a slight upregulation (1.45-fold) was seen in LUAD, whereas it was significantly downregulated in LUSC (0.064-fold)." (PMID 30845770, 2019).
metastatic melanoma (1 paper, 2019). A melanoma that has spread from its primary site to another anatomic site. "Cx32 (GJB1) protein was detected both in the vertical growth phase WM983/A and in the metastatic melanoma lines A2058 and HT199 as a granular and/or diffuse cytoplasmic reaction, while primary melanocytes were negative." (PMID 30717194, 2019).
polyneuropathy (1 paper, 2013). A disease or disorder affecting more than one nerve. "Independent of gender, patients with GJB1 mutations are represented in all polyneuropathy groups with the majority, however, in the mixed category." (PMID 24053775, 2013). "Patients showing demyelinating or mixed polyneuropathy/intermediate nerve conduction velocities, and those in whom the polyneuropathy type is uncertain, should be tested with PMP22 MLPA and DNA sequencing of the MPZ and GJB1 genes." (PMID 24053775, 2013). "Genetic testing was performed according to polyneuropathy type; demyelinating/mixed: PMP22 duplication, MPZ, EGR2, LITAF, NEFL, PMP22, GJB1, axonal: MFN2, MPZ, NEFL, and GJB1." (PMID 24053775, 2013).
Sensorimotor neuropathy (1 paper, 2023). "Most studies on Gjb1 focus on loss-of-function mutations, as they cause the sensorimotor neuropathy Charcot–Marie–Tooth type 1." (PMID 36831303, 2023).
Tremor (1 paper, 2014). An unintentional, oscillating to-and-fro muscle movement about a joint axis. "Another exception was a 42 year old female with CMT and a c.490C > T (p.Arg164Trp) mutation in the GJB1 gene who had tremor from early childhood, particularly of the head, muscular cramps and fasciculation’s (clinical group 4)." (PMID 24444136, 2014).
tumor (43 papers, 2009 to 2026). "An increase in Connexin 26 (encoded by Gjb2 gene) has also been found to be related to apoptosis of tumor cells (encoded by Gjb1 gene)." (PMID 35563241, 2022). "In one study, deficiency of the Connexin32 (encoded by Gjb1 gene) was found to induce tumor formation in the lungs and liver." (PMID 35563241, 2022). "The findings demonstrated that both GJA5 and GJB1 exhibited decreased expression in tumor tissues and elevated expression in normal tissues (p< 0.001)." (PMID 38454924, 2024). "Employing the TS dataset, a comprehensive analysis was conducted to examine the differences in gene expression between GJA5 and GJB1 in tumor tissues and normal tissues." (PMID 38454924, 2024). "Previous studies have disclosed that GJB1 exerts anti-apoptotic and pro-tumor effects by interacting with it." (PMID 37817158, 2023). "Given the results of the differential expression analysis, we speculated that GJA5 and GJB1 act as tumor suppressors in ccRCC." (PMID 38454924, 2024). "Furthermore, the high expression of GJB1 that is observed at the invasive margin relative to other intra-tumour regions could also contribute to neo-angiogenesis, as this gene is known to mediate the process of endothelial cell intercommunication." (PMID 29156557, 2017). "These genes include three tumour suppressors (DMBT1, MTUS1, and KLRC1), two genes involved with cell communication and myelin (GJB1 and KLK6), and a P450 monooxygenase involved in the synthesis of cholesterol and lipids (CYP4F12)." (PMID 37628980, 2023).
cancer (27 papers, 2013 to 2026). A tumor composed of atypical neoplastic, often pleomorphic cells that invade other tissues. "The Pan-cancer analysis revealed that GJA5 exhibited the highest expression level in ccRCC, whereas GJB1 was the 12th highest in terms of expression in ccRCC." (PMID 38454924, 2024). "In contrast, expression of GJB1 in the Cell was not significantly different in cancer and non-cancer samples." (PMID 36765747, 2023).
peripheral neuropathy (24 papers, 2012 to 2025). A disorder affecting the peripheral nervous system. "Gjb1−/− mice treated with lentiviral vectors encoding the GJB1 gene after the onset of peripheral neuropathy showed improved motor performance at 10 months." (PMID 40940747, 2025). "Among these GJB1 variants, despite the peripheral neuropathy found in all probands, the carrier of frameshift mutation exhibits rare CNS abnormalities." (PMID 36225735, 2022). "The X-linked dominant form of CMT type 1 (CMT1X), usually caused by mutations in the gap junction beta-1 (GJB1) gene, is the second most common form of inherited peripheral neuropathy and accounts for approximate 10% of all CMT cases." (PMID 36225735, 2022). "CMT1X is an inherited peripheral neuropathy caused by mutations in the GJB-1 gene thatencodes for connexin 32 (Cx32)." (PMID 34612709, 2021). "In conclusion, GJB1 mutations actually represent a spectrum of disease, including patients with either peripheral neuropathy or CNS involvement, or both." (PMID 32010055, 2019). "The X-linked form of Charcot-Marie-Tooth disease type 1 (CMTX1) is an inherited peripheral neuropathy that arises in patients with mutations in the gap-junction beta-1 gene (GJB1)." (PMID 31842800, 2019). "Discussion:GJB1 mutations form a clinical spectrum, including most patients with peripheral nerve involvement, those with both peripheral neuropathy and CNS involvement, and patients with CNS involvement only." (PMID 32010055, 2019). "Our case series of patients with GJB1 mutation include typical CMTX1 patients with only peripheral neuropathy, patients with both peripheral and possibly CNS involvement, and interestingly, one patient manifesting only recurrent CNS symptoms and signs." (PMID 32010055, 2019). "We describe serial cases of GJB1 mutation which form a clinical spectrum, including most patients with only peripheral nerve involvement, patient with both peripheral neuropathy and CNS involvement, and patient with only CNS involvement." (PMID 32010055, 2019). "In addition to peripheral neuropathy, several GJB1 mutations have been associated with subclinical-electrophysiological, or even clinical and/or magnetic resonance imaging (MRI) findings of chronic or transient CNS involvement." (PMID 31232168, 2019). "CMTX1, caused by mutations in the GJB1 gene, is primarily a peripheral neuropathy, but CNS involvement has been increasingly recognized." (PMID 39130881, 2024). "In this study, we used an AAV9 vector for targeted gene delivery to Schwann cells in order to treat the peripheral neuropathy in the Gjb1-null mouse model of CMT1X." (PMID 33692503, 2021). "Other gene replacement studies in inherited peripheral neuropathies, such as CMTX1, where lentiviral delivery of wild-type GJB1 showed therapeutic benefit, have underlined the potential of this technique, but have also highlighted the complexity of translating these strategies to clinical use." (PMID 41515914, 2025). "Even without evidence of peripheral neuropathy, GJB1 mutation should be considered as a differentiation." (PMID 32010055, 2019). "Furthermore, Gjb1-null mice with deletion of the Gjb1/Cx32 gene develop a progressive, predominantly motor demyelinating peripheral neuropathy beginning at about three months of age with reduced sciatic motor nerve conduction velocity (MNCV) and motor amplitude." (PMID 33692503, 2021).
genetic disorder (5 papers, 2014 to 2024). "CMT2 is a highly heterogeneous genetic disorder but 4 genes are the most frequently involved : the GJB1 (connexin-32), MPZ (P0 or myelin protein-zero), MFN2 (mitofusin 2) and GDAP1 (ganglioside-induced differenciation-associated protein 1)." (PMID 24804794, 2014).
disease of the peripheral nervous system (2 papers, 2023). "A number of these, including connexin 26 (Cx26)/GJB2, Cx29/Cx31.3/GJC3, Cx30/GJB6, Cx32/GJB1, Cx36/GJD2, Cx43/GJA1, Cx45/GJC1 and Cx47/GJC2 are expressed in the central and/or peripheral nervous system and mutations in a number of these cause central and/or peripheral nervous system disease." (PMID 37189458, 2023). "Although CMT is described as a disease of the peripheral nervous system, CNS involvement is reported in the literature in several CMT patients by variations in the MFN2, PMP22, GJB1, GDAP, MORC-2, NDRG1 and NEFL genes." (PMID 37238449, 2023).
GJB1 also shares sentences with these, for which no sentence is quoted: hepatocellular carcinoma (24 papers); glioma (10); liver cancer (8); liver disease (7); gastric cancer (5); acute kidney injury (4); cervical carcinoma (4); Cirrhosis (4); demyelinating disease (4); Hepatitis (4); renal cell carcinoma (4); cholestasis (3); colon cancer (3); ischemia (3); multiple sclerosis (3); non-alcoholic steatohepatitis (3); prostate tumors (3); amyotrophic lateral sclerosis (2); auditory neuropathy (2); bladder cancer (2); chronic hepatitis (2); Cognitive impairment (2); colorectal cancer (2); Encephalopathy (2); experimental autoimmune encephalomyelitis (2); infection (2); lymph node metastases (2); metabolic syndrome (2); neurodegenerative disease (2); oral cancer (2).
A further 74 diseases each share a sentence with GJB1 in 1 paper.